FAT1 (FAT atypical cadherin 1)
Diseases named in the same sentence as FAT1 in open-access papers (continued):
Sharing a sentence is not in itself a finding about the gene and the disease.
cyst (3 papers, 2019 to 2023). A sac-like closed membranous structure that may be empty or contain fluid or amorphous material. "This transgenic fish line allows fluorescent visualisation of the glomerulus and proximal tubules.The study revealed that knockdown of fat1 resulted in pronephric cyst development in morphants." (PMID 29502161, 2019). "The cyst burden in brain tissues at 3 weeks after T. gondii challenge was significantly lower in Fat-1 transgenic mice than in WT mice." (PMID 31500218, 2019). "Knockdown of fat1 in zebrafish caused a decrease in the amount of active RAC1 and CDC42 available and the addition of RAC1/CD42 was partially able to rescue the cyst phenotype observed." (PMID 29502161, 2019). "Moreover, Fat-1 transgenic mice exhibited lower cyst burden in the brain following infection with the avirulent strain ME49 than wild-type mice." (PMID 31500218, 2019).
depression (3 papers, 2018 to 2023). "In family 2, with two affected sisters diagnosed with major depressive disorder, we detected three rare variants shared by the two sisters in three genes implicated in affective disorders, including p.Ala4551Gly of FAT1, p.Val231Leu of HOMER3, and p.Ile185Met of GPM6B." (PMID 37511534, 2023). "Instead, we saw three rare variants that might be relevant to major depressive disorder, including p.Ala4551Gly of FAT1, p.Val231Leu of HOMER3, and p.Ile185Met of GPM6B." (PMID 37511534, 2023). "Two missense events in Fat1 were exclusive found in controls but not CSDS, which might affect its protein function or structure., and its human ortholog FAT1 is associated with nicotine dependence and major depression." (PMID 34093668, 2021). "In the future, we should further explore the specific mechanism by which n-3 PUFAs affect anhedonic behavior, for example the function of dopaminergic system and serotonin transporter protein expression in Fat-1 mice, which are related to anhedonia in depression." (PMID 30248907, 2018).
endometrial cancer (3 papers, 2017 to 2025). Primary or metastatic malignant neoplasm involving the endometrium (mucous membrane that lines the endometrial cavity). "The variant frequency for WT1 was fourth in endometrial cancer and sixth in CRC, while FAT1 was second in endometrial cancer and seventh in CRC." (PMID 40627234, 2025).
injury (3 papers, 2014 to 2016). Damage inflicted on the body as the direct or indirect result of an external force, with or without disruption of structural continuity. "In this study, we used fat-1 transgenic mice rich in endogenous n-3 PUFAs to examine the role of n-3 PUFAs in immune-mediated liver injury." (PMID 27679638, 2016). "Since T cells activation plays a significant role in Con A-induced hepatitis, the amelioration of Con A-induced liver injury in fat-1 transgenic mice may also be related to the selective inhibition of activated T lymphocytes by n-3 PUFAs." (PMID 27679638, 2016). "Improved motor performance has been observed after focal cerebral ischemia and neonatal hypoxic-ischemic brain injury and spinal cord injury after treatment with omega-3 fatty acids and in peripheral nerve injury in fat-1 transgenic mice that have elevated endogenous omega-3 fatty acid level." (PMID 24475126, 2014).
Insulin resistance (3 papers, 2013 to 2025). Increased resistance towards insulin, that is, diminished effectiveness of insulin in reducing blood glucose levels. "Nevertheless, in both male and female offspring weaned to control diet, the maternal fat-1 transgene conferred some protection from insulin resistance, where WT-HF offspring displayed elevated glucose levels during the insulin tolerance test." (PMID 32183350, 2020). "While the offspring from WT-HFD mothers weaned onto CD demonstrated increased weight gain (P<0.05), body and liver fat (P<0.05 and P<0.001, respectively), and whole body insulin resistance (P<0.05), these were prevented in WT offspring from Fat1-HFD mothers." (PMID 23825686, 2013). "Notably, the Fat-1 transgene increases endogenous n-3 PUFAs to protect Fat-1 transgenic mice from high-fat diet (HFD)-induced insulin resistance, inflammation, and MAFLD." (PMID 40052160, 2025). "Male WT offspring from Fat1-HFD mothers demonstrated less weight gain, adiposity, fatty liver, adipose tissue macrophages, hyperinsulinemia, and insulin resistance." (PMID 23825686, 2013).
invasive breast carcinoma (3 papers, 2012 to 2021). A carcinoma that infiltrates the breast parenchyma. "FAT1 repression in cancer occurs due to homozygous deletion or epigenetic silencing and is preferentially downregulated in invasive breast cancer." (PMID 32117864, 2020). "FAT1 mRNA level in ductal carcinoma in situ is significantly higher than that in invasive breast cancer and FAT1 knockdown promotes progression from ductal carcinoma in situ to invasive breast cancer." (PMID 23076869, 2012).
lung squamous cell carcinoma (3 papers, 2021 to 2024). "Moreover, a recent study proposed that deletion of FAT1 may cause upregulated EMT (Epithelial Mesenchymal Transition) status, tumor stemness, and metastatic ability in lung squamous cell carcinoma." (PMID 33808631, 2021).
oesophageal cancer (3 papers, 2017 to 2021). "The expression levels of PTPN14 and FAT1 were low in the tissues of esophageal carcinoma, but high in the adjacent tissues of esophageal carcinoma." (PMID 34712552, 2021). "The results showed that FAT1 protein was highly expressed in the adjacent tissues of esophageal carcinoma, but low in esophageal carcinoma tissues." (PMID 34712552, 2021). "MLL3 and FAT1 share connections across several cancer types, with both having several interaction in uterine cancer, while MLL2 exhibits many connections for stomach, and XYLT2 for oesophageal cancer." (PMID 30341300, 2018).
sarcoma (3 papers, 2017 to 2025). A usually aggressive malignant neoplasm of the soft tissue or bone. "One of the mutations present in our patient’s tumor was a loss-of-function mutation in FAT1, which encodes a tumor suppressor proto cadherin involved in regulating several key pathways in cancer, including in sarcomas." (PMID 40248199, 2025). "Although its role as a predictive marker in sarcoma has not been investigated, the durable response of our patient to pembrolizumab and the correlation with other more established predictive markers suggests that FAT1 could serve as a potential marker to predict response to ICIs in sarcoma patients." (PMID 40248199, 2025).
T-cell lymphoma (3 papers, 2020 to 2022). "FAT1 mutations spanned over the two main GATA3/TBX21 subgroups of peripheral T-cell lymphomas not otherwise specified." (PMID 31028364, 2020).
acute leukemia (2 papers, 2022). A clonal (malignant) hematopoietic disorder with an acute onset, affecting the bone marrow and the peripheral blood. "FAT1 was shown to be aberrantly expressed in pediatric patients with acute leukemia, whereas hematopoietic progenitors from healthy donors lacked the FAT1 expression." (PMID 35646625, 2022).
adenoma (2 papers, 2022 to 2023). A neoplasm arising from the epithelium. "Likewise, FAT1 is highly expressed in colon and rectal cancer, mainly on the plasma membrane, and also in adenoma samples, with predominant intracellular pattern, but FAT1 is negligible or not detectable in normal tissues." (PMID 35647082, 2022).
angiosarcoma (2 papers, 2023 to 2025). A malignant tumor arising from the endothelial cells of the blood vessels. "Some studies propose that FAT1 inhibits mitochondrial respiration, a process involved in vascular muscle proliferation, but its role in angiosarcoma remains to be clarified." (PMID 41301029, 2025).
Anophthalmia (2 papers, 2021 to 2022). Absence of the globe or eyeball. "In addition, holoprosencephaly and anophthalmia are observed in Fat1 deficient mice." (PMID 36042367, 2022).
autism (2 papers, 2014 to 2021). Persistent deficits in social interaction and communication and interaction as well as a markedly restricted repertoire of activity and interest as well as repetitive patterns of behavior. "Furthermore, we investigated the association of FAT1 with ASD by analyzing its expression in neural precursor cells (NPCs) differentiated from induced pluripotent stem cells (iPSCs) derived from individuals with autism compared to those from control individuals." (PMID 34100899, 2021). "Our findings suggest a potential function of FAT1 in the cerebellum during early postnatal development and strengthen its association with ASD by showing altered expression levels of FAT1 in autism-specific NPCs." (PMID 34100899, 2021). "Additional alterations were found in previously reported autism candidate genes, including three genes with alterations in multiple families (CEP290, CSMD1, FAT1, and STXBP5)." (PMID 24410847, 2014).
autism spectrum disorder (2 papers, 2021 to 2023). A spectrum of developmental disorders that includes autism, and Asperger syndrome. "Recently, genetic variations in FAT1 have been associated with neurological disorders, such as bipolar disorder and autism spectrum disorder (ASD)." (PMID 34100899, 2021). "Other studies reported that FAT1 was implicated in autism spectrum disorders." (PMID 37511534, 2023). "Genetic studies have linked FAT1 (FAT atypical cadherin 1) with autism spectrum disorder (ASD); however, the role that FAT1 plays in ASD remains unknown." (PMID 34100899, 2021).
B-cell acute lymphocytic leukemia (2 papers, 2014 to 2023). "Upstream Hippo inputs have also been found to have hypermethylated promoters with reduced gene expression, including FAT4 in breast cancer and KIBRA and FAT1 in B-cell acute lymphocytic leukemia (B-ALL)." (PMID 25097728, 2014).
B-cell lymphomas (2 papers, 2021). "In this study in B-cell lymphomas, we also found the low mutation frequencies of the major components of Hippo pathway like LATS1 (1%), LATS2 (1%), YAP1 (1%), and FAT1 (6%)." (PMID 34926267, 2021).
bipolar affective disorder (2 papers, 2014 to 2023). "FAT1 has been associated with bipolar affective disorder and ASD, and is essential for controlling developmental cell proliferation." (PMID 24962056, 2014). "Two studies reported that FAT1 is a susceptibility gene for bipolar disorder, although this association was not replicated in the other study." (PMID 37511534, 2023).
cholangiocarcinoma (2 papers, 2014 to 2020). A carcinoma that arises from the intrahepatic biliary tree (intrahepatic cholangiocarcinoma) or from the junction, or adjacent to the junction, of the right and left hepatic ducts (hilar cholangiocarcinoma). "Other studies, however, pointed to a potential tumor suppressor role, as loss of heterozygosity and homozygous deletions were detected in astrocytic cancers and in oral tumors, whereas loss of membraneous Fat1 was reported to correlate with more aggressive intrahepatic cholangiocarcinomas." (PMID 24625754, 2014).
gastric tumors (2 papers, 2016 to 2020). "All H. pylori-infected mice had developed variable sized gastric tumors, whereas only 30% of Fat-1 TG mice developed gastric tumors and those were smaller than those in WT mice." (PMID 27528223, 2016).
hyperlipidemia (2 papers, 2016 to 2025). "Since Fat-1 executed beneficial function on hyperlipidemia, it was rational for us to investigate the effect of the expression of Fat-1 on MAFLD in WT hamsters." (PMID 40052160, 2025).
liver fibrosis (2 papers, 2014 to 2025). "Sirius Red staining and CD68 immunofluorescence staining consistently showed that PPARα inhibition reversed the improvement exerted by Fat-1 on liver fibrosis and inflammation." (PMID 40052160, 2025). "Additionally, Fat-1 significantly relieved liver fibrosis and macrophage infiltration in the liver sections, as demonstrated by Picrosirius Red staining and CD68 immunofluorescence staining, respectively." (PMID 40052160, 2025).
membranous glomerulonephritis (2 papers, 2023 to 2024). A slowly progressive inflammation of the glomeruli characterized by immune complex deposits at the glomerular basement membrane, resulting in a thickened membrane, and nephrotic syndrome. "Interestingly, an analysis of human kidney biopsies showed that normal glomeruli predominantly express wild type FAT1 over FAT1(+12), whereas minimal change disease, focal segmental glomerulosclerosis, and membranous glomerulonephritis exhibit the inverse pattern of expression." (PMID 37371091, 2023). "In patients with membranous nephropathy (MN) who have undergone allogeneic HSCT, a new antigen called protocadherin FAT1 has been identified." (PMID 39118046, 2024).
osteosarcoma (2 papers, 2018 to 2019). A usually aggressive malignant bone-forming mesenchymal neoplasm, predominantly affecting adolescents and young adults. "In this study, we observed significant upregulation of circFAT1 originating from exon 2 of the FAT1 gene in human osteosarcoma tissues and cell lines." (PMID 30514309, 2018).
papillary thyroid cancer (2 papers, 2023 to 2025). "On the other hand, a circular RNA species derived from the FAT1 locus, circFAT1, is elevated in colorectal cancer tissues and cells as well as in papillary thyroid cancer cell lines, and circFAT1 knockdown impairs migration and invasion in both colorectal and papillary thyroid cancer cell lines." (PMID 37371091, 2023).
penile cancer (2 papers, 2020 to 2021). A primary or metastatic malignant neoplasm that affects the penis.
T-cell acute leukemia (2 papers, 2020 to 2023). "The FAT1 gene is mutated in 12–16% of T-cell acute leukemia (T-ALL) and aberrantly expressed in about 54% of T-ALL cases contrasted with absent expression in normal T-cells." (PMID 36653435, 2023). "FAT1 has been reported recurrently mutated across multiple types of cancers, including T-cell acute lymphoblastic leukemia and it appears to potently suppress cancer cell growth by binding beta-catenin and antagonizing the nuclear localization." (PMID 31028364, 2020).
acinar cell carcinoma (1 paper, 2015). "Moreover, we identified germline missense mutations in FAT1 and FAT3 resulting in loss of the wild-type allele, which suggests that these germline mutations are likely to be selected and to contribute to the phenotype of acinar cell carcinoma." (PMID 25743105, 2015). "Then, we performed target sequencing analyses for the entire coding regions of BRCA1, BRCA2, FAT1, and FAT4 via a semiconductor sequencer in an additional 4 cases of acinar cell carcinoma, using archival formalin-fixed and paraffin-embedded (FFPE) tissues." (PMID 25743105, 2015).
astrocytic tumor (1 paper, 2012). A glial tumor of the brain or spinal cord showing astrocytic differentiation. "The expression of FAT1, on the other hand, has been found to be reduced in astrocytic tumors." (PMID 23145530, 2012).
autosomal dominant deafness (1 paper, 2021). "FAT1 is, among other genes, located in the autosomal dominant deafness locus DFNA24, which has been mapped to an 8.1-Mb interval in the 4q31.1–q35.2 region." (PMID 33418956, 2021).
bladder urothelial cancer (1 paper, 2022).
Burkitt lymphoma (1 paper, 2016). A rare form of malignant mature B-cell non-Hodgkin lymphoma. "Interestingly, FAT1 has been reported in resistance in CLL and SMARCA4 was associated with Burkitt lymphoma." (PMID 27285986, 2016).
cervical squamous cell carcinoma (1 paper, 2021). A squamous cell carcinoma arising from the cervical epithelium. "In cervical squamous cell carcinoma, FAT1 positively correlated with SOX4, and upregulated it to promote migration and invasion of cancer cells." (PMID 34580376, 2021).
chronic atrophic gastritis (1 paper, 2016). Atrophic gastritis that is persistent and long-standing. "There were no prominent changes in H. pylori-infected Fat-1 TG mice, only mild gastritis and focal erosive changes were observed." (PMID 27528223, 2016).
Chronic colitis (1 paper, 2016). A chronic inflammatory disease of the large intestine (colon, cecum and rectum). "In the current study, we showed that mice engineered to carry a fat-1 gene from the roundworm C. elegans, adding a double bond into an unsaturated fatty acid hydrocarbon chain and converting ω-6 to ω-3 fatty acids, showed significant protection from chronic colitis-associated carcinogenesis." (PMID 27566583, 2016).
COVID-19 (1 paper, 2021). A disease caused by infection with severe acute respiratory syndrome coronavirus 2. "Two other fAABs that were also present in 29 (90%) of the 31 investigated post-COVID-19 patients were directed against the angiotensin II AT1 receptor (fAT1-AAB) and the angiotensin 1-7 MAS receptor (MAS-AAB)." (PMID 33880442, 2021).
cystic kidney disease (1 paper, 2025). A congenital or acquired kidney disorder characterized by the presence of renal cysts. "Seven genes (3%) had no entries in OMIM (DLG5 in renal ciliopathies and cystic kidney diseases; and 6 in the proteinuric kidney diseases [APOE, DLC1, FAT1, ITSN1, PODXL and TNS2]) and were excluded." (PMID 40303230, 2025).
deafness (1 paper, 2013). An inherited or acquired condition characterized by the complete loss of the ability to hear from one or both ears. "FAT1 lies near the critical locus involved in causing FSHD, and Fat1 mutant mice also show retinal vasculopathy, mimicking another symptom of FSHD, and showed abnormal inner ear patterning, predictive of deafness, reminiscent of another burden of FSHD." (PMID 23785297, 2013).
diabetic neuropathy (1 paper, 2015). A chronic, pathological complication associated with diabetes mellitus, where nerve damages are incurred due to diabetic microvascular injury involving small blood vessels that supply these nerves, resulting in peripheral and/or autonomic nerve dysfunction. "Our results suggest that autophagic activity in fat-1 transgenic mice might be important to defense mechanisms activated by diabetic neuropathy in vivo." (PMID 26503303, 2015).
diaphragmatic hernia (1 paper, 2018). A congenital or acquired weakness or opening in the diaphragm which allows abdominal contents to protrude into the chest cavity; congenital diaphragmatic hernias are caused when the embryonic diaphragm fails to fuse. "The fact that Fat1 deficiency did not alter diaphragm development or lead to diaphragmatic hernias such as those occurring in the absence of Gata4 make it unlikely for Fat1 to be required in the Gata4+/diaphragm CT subtype." (PMID 29768404, 2018).
endometrioid carcinoma (1 paper, 2021). "High-grade endometrioid carcinoma tiles with diffuse solid growth and low nuclear grade were depicted in the FAT1-mutated cluster, while low-grade endometrioid carcinomas with gland formation, low nuclear grade, and cribriform architecture were in the wild-type cluster." (PMID 34622237, 2021).
endometriosis (1 paper, 2013). The growth of functional endometrial tissue in anatomic sites outside the uterine body. "In this study, we showed the suppressive effect of omega-3 PUFAs in the mouse endometriosis model by making full use of two types of genetically modified mice: fat-1 and 12/15-LOX KO mice." (PMID 24039864, 2013).